TBK1 (TANK binding kinase 1)
Diseases named in the same sentence as TBK1 in open-access papers (continued):
Sharing a sentence is not in itself a finding about the gene and the disease.
cervical carcinoma (12 papers, 2020 to 2025). A carcinoma arising from either the exocervical squamous epithelium or the endocervical glandular epithelium. "Activating the STING/TBK1 pathway suppresses tumor growth in HPV-positive cervical cancer by degrading HPV16/18 E7 oncoproteins." (PMID 39949780, 2025). "Activating the STING/TBK1 pathway in cervical cancer cells induces the degradation of HPV16 and HPV18 E7 oncoproteins, which are critical for the tumorigenic properties of HPV-related cancers." (PMID 39949780, 2025). "Functionally, activated STING inhibits cervical cancer cell proliferation by downregulating E7 oncoprotein in a TBK1-dependent manner and potentially synergizes with radiation to achieve better effects for antitumor." (PMID 39445027, 2024). "The latest research also indicates that activation of STING-TBK1 (TANK-binding kinase 1) promotes the ubiquitin-proteasome degradation of the E7 oncoprotein, thereby inhibiting the growth of cervical cancer." (PMID 39445027, 2024). "In contrast to the high activation of TBK1 in the spinal cord neurons, endogenous TBK1 was generally inactivated in cultured cell lines, including human cervical carcinoma HeLa, mouse neuroblastoma Neuro2a, and human neuroblastoma SH-SY5Y." (PMID 37967220, 2023). "This study is focused on performing the multitargeted molecular docking of FDA-approved drugs with the three crucial proteins TBK1, DNA polymerase epsilon, and integrin α-V β-8 of cervical cancer." (PMID 38100507, 2023). "TBK1’s intricate relationship with inflammation, cell proliferation, and evasion of immune surveillance adds a multifaceted dimension to its role in cervical cancer." (PMID 38100507, 2023). "The molecular docking revealed strong binding affinities and specific interactions between Pixantrone Maleate and all three target proteins, DNA polymerase epsilon, Integrin alpha-v beta-8, and TBK1, involved in cervical cancer." (PMID 38100507, 2023). "Human TBK1, a component of the innate immune response, has recently emerged as a potential protagonist in cervical cancer." (PMID 38100507, 2023). "A multitargeted drug design approach offers a promising strategy in the battle against cervical cancer that simultaneously can target epsilon B-subunit of DNA polymerase, Integrin alpha-v beta-8, and Human TBK1, making it possible to disrupt multiple pro-cancer signalling pathways." (PMID 38100507, 2023). "In addition, recent studies revealed the effect of TBK1 on promoting immunosuppression in lung and cervical cancer." (PMID 33679751, 2021). "Combining therapies targeting DNA polymerase epsilon B-subunit, Human TBK1, and Integrin alpha-v beta-8 could disrupt the pro-cancer signalling cascades while simultaneously addressing cervical cancer’s genomic instability and promising enhanced efficacy and reduced drug resistance." (PMID 38100507, 2023). "Within the intricate landscape of cervical cancer biology, three proteins have emerged as pivotal players, intricately woven into the fabric of this malignancy: epsilon B-subunit of DNA polymerase, Integrin alpha-v beta-8 and Human TBK1 (TANK-binding kinase 1)." (PMID 38100507, 2023). "For example, PD-L1 upregulation by STING-dependent activation of TBK1 was observed in HCC and in HPV-positive cervical cancer cells." (PMID 39001487, 2024).
colorectal cancer (12 papers, 2014 to 2025). A primary or metastatic malignant neoplasm that affects the colon or rectum. "The data indicate that dysregulation of the expression of multiple signaling cascade members that regulate IFN production, including TBK1, increases susceptibility to colorectal cancer (CRC)." (PMID 39161768, 2024). "In this study, high expression of MB21D1 was associated with poor prognosis in colorectal carcinoma, and high expression of TBK1 was associated with poor prognosis in lung adenocarcinoma and good prognosis in rectal adenocarcinoma." (PMID 34768716, 2021). "The expression of mRNA encoding IFI16, STING, TBK1, and IFN-β was significantly decreased in the colorectal cancer tissues in comparison to normal tissue in a cohort of Chinese colorectal cancer patients." (PMID 28748479, 2018). "Another example is pRB, a tumor suppressor that is targeted by miR-675 in colorectal cancer in which miR-675 acts as an oncogene and IkB kinase TBK1." (PMID 25889562, 2015). "TBK1 mRNA has been observed to be increased in some human colorectal cancers." (PMID 35395857, 2022). "Western blot analysis confirmed the increased expression of IFN-β and CXCL10 as well as phosphorylation of TBK1, IRFs, and STAT1 in FGFR4-overexpressing colorectal cancer cells." (PMID 40447617, 2025).
asthma (11 papers, 2015 to 2025). "The role of IKBKE signaling for the stiffness-induced phenotype was further tested using a pharmacological inhibitor of IKBKE, Amlexanox, a dual IKBKE/TBK1 inhibitor that is clinically used for the treatment of recurrent aphthous ulcers and asthma." (PMID 40468448, 2025). "TBK1 was involved in the pathogenesis of asthma induced by house dust mite-induced endoplasmic reticulum stress in one study." (PMID 40076567, 2025). "Immune transcriptome analysis of LNR125 treated BECs from individuals with asthma indicated that blocking IL-25 restored antiviral immunity with evidence of upregulation of ISGs, such as IRF7 and TBK1 and interleukin-1 receptor-associated kinase 2 (IRAK2)." (PMID 35508632, 2022). "Amlexanox, an IKBKE/TBK1 inhibitor developed to treat ulcers, allergic rhinitis and asthma, results in a G0/G1 arrest in glioblastoma cells and induction of apoptosis." (PMID 32324216, 2020). "As an inhibitor of IKK-ε and TBK1, amlexanox is an anti-inflammatory, anti-allergic, immunomodulator and used for treatment of ulcer, allergic rhinitis and asthma in clinic." (PMID 26338477, 2015). "In our study, we found that GSDMB, the asthma risk gene located in the 17q21, promotes the activation of mtDNA-induced cGAS-STING pathway via facilitating the translocation of STING into Golgi and subsequent interaction with TBK1." (PMID 38737375, 2024). "For instance, it was recently shown that cGAMP triggered HDM extract-induced asthma in mice via IL-33 in a TBK-1 dependent manner which could be antagonized by the bona fide TBK-1 inhibitor amlexanox." (PMID 37090735, 2023). "Together, these findings suggest that TBK1 inhibitors could be a promising class of anti-asthma drugs." (PMID 31616416, 2019).
diabetes (11 papers, 2008 to 2025). "Interestingly, we found that genetic inhibition of STING attenuates diabetes-induced phosphorylation of TBK1, IKK, IκB, and NF-κB, which is associated with reduced iNOS and ICAM-1 expression along with decreased superoxide production and leukostasis in STING-perturbed diabetic mice." (PMID 37345657, 2023). "We found the expression of p-IRF3 and p-TBK1 was significantly increased in the retinas of diabetic mice 2 months after the induction of diabetes, prior to the development of microvascular injury." (PMID 37345657, 2023). "STING contributes to diabetes-induced retinal vascular cell injury through the STING/TBK1/IRF3/IFN-β signaling pathway." (PMID 37345657, 2023). "A clinical trial was initiated with amlexanox, an inhibitor of IKKε and TBK1, in patients with diabetes and the results showed improved glucose control in the treated patients." (PMID 30223576, 2018). "In some cases, gene expression differed significantly between groups from early in the disease course, for example, Tbk1 from 6 weeks of age, and in other cases expression diverged later, for example, Lamp2 at 12 weeks and diabetes onset." (PMID 26366287, 2015). "It is likely that the difference in expression of the lymphocyte-enriched genes Psmc2, Dag1 and Tbk1 in mice with early or late diabetes onset was under-estimated by the analysis in whole blood, in which lymphocytes are under-represented." (PMID 26366287, 2015). "Furthermore, in clinical studies of diabetes-induced AS, hyperglycemia activates TBK1, thereby exacerbating AS by inducing IL17/IL10-mediated inflammatory responses via TBK1-HIF-1α signaling in macrophages and dendritic cells." (PMID 40076567, 2025). "Thus, the ability of TBK1 to negatively regulate AMPK can be critical for reducing TET2 and associated epigenetic changes during the progression from pre-diabetes, overt diabetes, and cancer." (PMID 30791439, 2019). "Nevertheless, our data suggest that diabetes-induced retinal capillary lesions may occur through STING/TBK1–regulated REC senescence through the IRF3/IFN-β and NF-κB pathways, making STING pivotal to connecting multiple signaling pathways that contribute to DR pathogenesis." (PMID 37345657, 2023). "Thus, a careful dissection and elucidation of TBK1- and/or IKKε-controlled signaling networks will shed light on modulating β-cell survival with concomitant increase in functional β-cell mass, opening up new avenues of therapies for mitigating diabetes." (PMID 30349097, 2018). "To further elucidate the molecular mechanism(s) by which STING promotes diabetes-induced retinal vascular cell injury, we investigated the role of downstream effectors of the cGAS/STING pathway, including TBK1 and IRF3." (PMID 37345657, 2023). "We provide evidence that elevated levels of IFN-β are present in the retinas of both human DR donors and diabetic mice and that genetic inhibition of STING abolished diabetes-induced secretion of IFN-β and REC senescence; this correlated with a reduction in the levels of p-TBK1 and p-IRF3." (PMID 37345657, 2023). "Collectively, these results suggest that diabetes-induced REC senescence may be due to the activation of STING and the subsequent increase IFN-β through TBK1/IRF3 signaling." (PMID 37345657, 2023). "Some genes such as Sirt7, Tbk1 and Lamp2 were significantly overexpressed in the group developing diabetes after 17 weeks, but expression did not correlate with time of diabetes onset." (PMID 26366287, 2015).
hepatocellular carcinoma (11 papers, 2021 to 2025). A malignant tumor that arises from hepatocytes. "In addition, high expression of TBK1 in tissues from hepatocellular carcinomas were shown to be associated with reduced tumor-infiltrating CD8+ T-cells and increased levels of immunosuppressive markers." (PMID 39061024, 2024). "Tiliroside hindered the development of HepG2 tumors in both subcutaneous and orthotopic xenograft tumor models of HCC which further enhanced the effectiveness of sorafenib in treating hepatocellular carcinoma by targeting TBK1 to trigger ferroptosis." (PMID 38738178, 2024). "Our previous study demonstrated that high TBK1 expression enhanced hepatocellular carcinoma invasion and predicted poor prognosis." (PMID 36928362, 2023). "High TBK1 expression was correlated with poor prognosis and contributed to the vascular invasion of hepatocellular carcinoma." (PMID 36988258, 2023). "Univariate and multivariate Cox regression analyses of TANK-binding kinase 1 (TBK1) mRNA expression for overall survival (OS) in patients with hepatocellular carcinoma (HCC) from The Cancer Genome Atlas (TCGA) data set." (PMID 33679751, 2021). "This suggests that the absence of CD81 can compensate for TBK1-mediated inhibition of proliferation of Huh7.5 hepatoma cells." (PMID 38357447, 2024). "However, the detailed function and molecular mechanisms of TBK1 in hepatocellular carcinoma (HCC), especially the resistance of HCC cells to molecular-targeted drugs, are almost unknown." (PMID 35747750, 2022). "Similarly, in hepatocellular carcinoma (HCC) patients, TBK1 expression was found to be higher in tumor tissues compared to adjacent normal tissues." (PMID 35395857, 2022). "However, the prognostic role of TBK1 and its relationship with immune cell infiltration in hepatocellular carcinoma (HCC) remain unclear." (PMID 33679751, 2021). "The treatment of Hepa1 hepatoma cells with TBK1 inhibitors did not affect the amount of BACH1 mRNA." (PMID 38673728, 2024). "In hepatocellular carcinoma (HCC), TBK1 expression levels are also significantly higher than in normal liver tissue and are associated with a poorer prognosis." (PMID 40076567, 2025).
normal tension glaucoma (11 papers, 2011 to 2024). "Mutations in OPTN (optineurin) and TBK1 (TANK-binding kinase 1) genes, have been associated to normal tension glaucoma, which give rise to glaucomatous neurodegeneration in the absence of increased IOP." (PMID 37034386, 2023). "Certain missense mutations in optineurin/OPTN and amplification of TBK1 are associated with normal tension glaucoma." (PMID 26376340, 2015). "Both optineurin (OPTN) and TANK-binding protein 1 (TBK1) have been genetically linked to patients with normal tension glaucoma." (PMID 24699552, 2014). "Of note, TBK1 copy number increase mutations are found among the normal-tension glaucoma patients." (PMID 36828933, 2023). "Importantly, mutations in OPTN, and a gene duplication of TBK1 leading to increased expression, have been linked to normal tension glaucoma." (PMID 24699552, 2014). "OPTN, TBK1, and METTL23 are responsible for early onset normal-tension glaucoma with autosomal dominant inheritance, characterized by significant optic atrophy despite normal IOP." (PMID 38671671, 2024).
rheumatoid arthritis (11 papers, 2012 to 2025). A chronic, systemic autoimmune disorder characterized by inflammation in the synovial membranes and articular surfaces. "A rheumatoid arthritis animal model has been especially helpful in proving a strong positive relationship between TBK1 and this disease." (PMID 23304064, 2012). "In conditions of increased TBK1 activity, strongly upregulated Syk might also be involved in inflammatory diseases such as neuroinflammation, rheumatoid arthritis, and lung inflammation." (PMID 39493293, 2024). "TBK1-depleted fibroblast-like synoviocytes revealed reduced capacity for IRF-3-mediated induction of IFN-β and IP-10, suggesting that, particularly, TBK1 is involved in the pathogenesis of rheumatoid arthritis." (PMID 25997745, 2015). "Furthermore, TBK1 knockout fibroblast-like synoviocytes (FLS) show decreased expression levels of IFN-β and IP-10, which are known to contribute to the occurrence of rheumatoid arthritis." (PMID 23304064, 2012).
type 2 diabetes (11 papers, 2017 to 2025). "Several studies have implicated the role of TBK1 in metabolic diseases, including NAFLD and type 2 diabetes." (PMID 37028764, 2023). "Thus, for example, an IKK/TBK1 inhibitor has been tested in obese individuals with type 2 diabetes showing encouraging results." (PMID 34884808, 2021). "The TBK1/IKKɛ -NF-κB is the most reported central inflammation pathway inducing the release of proinflammatory cytokines during positive energy balance, leading to generation of type 2 diabetes." (PMID 28319103, 2017). "Knockout of the downstream targets of cGAS–STING, TBK1, or IRF3303, 304 or inhibition of IκB kinase ε (IKKε) and TBK1 with amlexanox, resulted in significant weight loss, enhanced insulin sensitivity, and improved glucose tolerance in obese mice (and some type II diabetic patients)." (PMID 38525112, 2024). "A study analyzing gene expression between individuals with type II diabetes and controls found differential expression of the RIG‐I‐like receptor signaling pathway, highlighting the genes TBK1, ATG5, TANK, IL8, and MAVS." (PMID 40476695, 2025). "For type 2 diabetes PDN model, TBK1-siRNA, Caspase-1 inhibitor Ac-YVAD-cmk or TBK1 inhibitor amlexanox (AMX) were delivered by intrathecal injection or intragastric administration." (PMID 39030571, 2024).
colitis (10 papers, 2012 to 2025). Inflammation of the colon. "By suppressing STING oligomerization, it blocks TBK1 recruitment and IRF3/NF-κB nuclear translocation, thereby slowing colitis progression and colitis-associated colon cancer." (PMID 40621423, 2025). "Mice with myeloid cell specific TBK1 and IKKε inhibition showed ileitis and colitis that were almost completely inhibited by homozygous expression of kinase-inactive RIPK1." (PMID 38167258, 2024). "Treatment with RU.521 can also reduce cGAMP levels and decrease STING, TBK1, and IRF3 phosphorylation during colitis, confirming the potential pathogenic role of cGAS–STING signaling pathway in colitis." (PMID 37566032, 2023). "The level of phosphorylated TBK1 in mice with colitis was increased in DMXAA group, and ANP inhibited phosphorylation of TBK1 compared with DMXAA group." (PMID 35280696, 2022). "Modulating the STING/TBK1 pathway to induce inflammatory cell apoptosis can be an effective means of treating colitis." (PMID 34829556, 2021). "Importantly, inhibition of NF-κB, p-TBK1, and TBK1 at protein levels and transcription of Ifit-1, and Ifn-β were observed in the colon of cGAS deficient DSS-colitis mice." (PMID 34158863, 2021). "In addition to this result, our group has also discovered that high levels of active TBK1 are expressed in the DSS-induced colitis model, the HCl/EtOH-induced gastritis model, the LPS-induced hepatitis model, and the collagen type-II-induced arthritis model (unpublished data)." (PMID 23304064, 2012). "Collectively, these findings indicate that STING, TBK1, and RELA are critical components of IL-10 activation by LGG in the context of colitis." (PMID 39895628, 2025). "In our experiments, TBK1 phosphorylation levels were reduced in the spleens of mice with colitis, and the STING-TBK1 signaling pathway was inhibited, whereas the STING-TBK1 signaling pathway was activated and lymphocyte apoptosis was induced by PSE and PLE." (PMID 34829556, 2021). "In some inflammatory disease animal models, such as colitis and hepatitis animal models, levels of the active form of TBK1 are elevated compared to nondisease groups (unpublished data)." (PMID 23304064, 2012).